EZH2 (enhancer of zeste 2 polycomb repressive complex 2 subunit)
Diseases named in the same sentence as EZH2 in open-access papers (continued):
Sharing a sentence is not in itself a finding about the gene and the disease.
liver cancer (continued). "It has been reported that hsa_circ_0008450 inhibits the progression of liver cancer by sponging hsa-miR-214-3p to promote the expression of EZH2 protein." (PMID 35590240, 2022). "Our findings suggest that suppression of Dicer by the HOXB‐AS3/EZH2 complex plays a critical role in sorafenib resistance and cancer stemness in liver cancer." (PMID 35253323, 2022). "The low correlation between EZH2 and H3K27me3 and the repressed binding signal on DNA for EZH2 and H3K27me3 in HepG2 suggests the DNA binding ability of EZH2 was attenuated in liver cancer." (PMID 36578923, 2022). "During the occurrence of liver cancer, the expressions of enhancer of zeste homolog 2 (EZH2) and p57 gene of flies would change to some extent." (PMID 35321452, 2022). "In liver cancer, circ_0008450 enhanced tumor development by sponging miR-214-3p and increasing EZH2 expression." (PMID 35030969, 2022). "It is previously reported that lncRNA inhibits E-cadherin transcription by binding to EZH2 in liver cancer cells." (PMID 35414117, 2022). "MiR-1297 can target EZH2 to inhibit the proliferation of liver cancer cells and promote the apoptosis of liver cancer cells." (PMID 34568017, 2021). "EZH2 c.1544A>G and CCND1 c.839A>T were found in five liver cancer patients with the highest mutation frequency." (PMID 34604069, 2021). "Immunofluorescence staining demonstrated a higher expression and co-localization of EZH2 and H3K27me3 in liver cancer cell nuclei." (PMID 34725436, 2021). "For example, miR-98 can downregulate the Wnt/β-catenin signaling pathway through targeted inhibition on EZH2, ultimately suppressing the proliferation of liver cancer cells." (PMID 31966062, 2020). "The results also pointed that epigenetic silencing of ZIC4 by EZH2 mediated H3K27me3 is an important mechanism in human liver cancer, which are very important for subsequent clinical research." (PMID 33097694, 2020). "In conclusion, this study indicates for the first time to the best of our knowledge, that miR-101 can inhibit the phosphorylation level of ERK1/2 through targeted inhibition on EZH2, ultimately suppressing the proliferation of liver cancer cells." (PMID 31966062, 2020). "For example, exosomal circRNA_100284 promoted liver cancer cell cycle and proliferation through microRNA-217/EZH2 axis." (PMID 31973767, 2020). "Our study indicated that epigenetic silencing of ZIC4 by EZH2 mediated H3K27me3 is an important mechanism in human liver cancer." (PMID 33097694, 2020). "Finally, we show that many genes associated with liver fibrosis and liver carcinogenesis are differentially responsive to the loss of Ezh1/Ezh2 in male compared to female liver, which may contribute to the observed sex-differences in the incidence and progression of liver cancer." (PMID 32428001, 2020). "EZH2 has been unraveled as a core factor in hepatocarcinogenesis, self-renewal of liver cancer stem cells (CSCs), and molecular targeted therapy." (PMID 32849835, 2020). "Ezh2 silences several tumor suppressor miRNAs that are down-regulated in liver cancer and it interacts with highly expressed oncogenic long non-coding RNAs (lncRNAs) to repress target genes in HCC." (PMID 32428001, 2020). "Specifically, EZH2 contributes to liver cancer through modulation of different tumor-suppressor microRNAs,44, 45 long noncoding RNAs,46 or regulating the cell cycle, among other processes." (PMID 30539787, 2019). "Another reason for doxorubicin resistance in liver cancer patients is downregulation of the tumor suppressor miR-101 resulting in increased protein expression of enhancer of zeste homolog 2 (EZH2)." (PMID 29967761, 2018). "Chromatin modifiers, in particular the polycomb-repressive complexes 2 subunit IEnhancer of zeste homolog 2 (EZH2), have been reported in many studies to be overexpressed in HCC samples and this is often associated with poor prognosis in liver cancer patients." (PMID 30035186, 2018).
liver cancer (continued). "Silencing EZH2 expression in liver cancer cells attenuated liver cancer proliferation and metastasis." (PMID 25226601, 2014). "Many HCC often arise within the background of liver fibrosis, so we detected the expression of 14-3-3σ and EZH2 in liver cancer with normal tissue and liver fibrotic tissue as control by RT-PCR, qRT-PCR, Western blot and immunohistochemistry." (PMID 25226601, 2014). "Overexpression of EZH2 usually occurs in a diverse of malignancies, including prostate, breast and liver cancers, especially in advanced cases." (PMID 22808286, 2012). "In the present study, we found that EZH2 mRNA was highly expressed in human liver cancer cell lines as well as in primary tumours from HCC patients." (PMID 15856046, 2005). "We first examined EZH2 mRNA expression in three human liver cancer cell lines and found sufficient EZH2 expression in all the cell lines." (PMID 15856046, 2005). "EZH2 overexpression also reverses fibrosis which is common in liver cancer." (PMID 41512022, 2026). "In addition, EZH2 overexpression in liver significantly improved glucose tolerance of the old mice, while in mouse liver cancer models, glucose tolerance in general is impaired due to misregulated metabolism." (PMID 41512022, 2026). "Given the association between EZH2 overexpression and embryonal histology, targeting EZH2 may offer a promising strategy to improve outcomes in this aggressive pediatric liver cancer." (PMID 40766612, 2025). "Ultimately, these findings may contribute to developing novel therapeutic strategies that could improve patient outcomes in HCC, emphasizing the importance of further investigations into the role of EZH2 in liver cancer biology." (PMID 41298718, 2025). "For instance, inhibiting EZH2 activity may restore immune cell function and improve the efficacy of immunotherapy for liver cancer." (PMID 40018411, 2025). "Moreover, HEIH enhances liver cancer cell proliferation by interacting with enhancer of zeste homolog 2 (EZH2) and modulating epigenetic modifications." (PMID 40060195, 2025). "EZH2 expression can affect the prognosis of patients with liver cancer." (PMID 39640777, 2024). "Given these insights, combination therapy is increasingly utilized, and our study adds to the growing evidence that targeting overexpressed EZH2 in liver cancer might prove effective in conjunction with other therapeutic modalities." (PMID 39516467, 2024). "EZH2 is closely related to the proliferation of liver cancer cells." (PMID 37268997, 2023). "This information supported the notion that EZH2/H3K27me3 might directly suppress these genes to regulate the cell cycle during CTD therapy for liver cancer." (PMID 37202806, 2023). "In addition, we demonstrated that HOTAIR recruits and binds to PRC2 (EZH2) to epigenetically silence miR-145-5p expression via H3K27me3 modification to promote liver cancer cell-EMT process and metastasis." (PMID 37576402, 2023). "To determine whether HOTAIR regulates miR-145-5p expression levels by binding with PRC2, we added si-EZH2 to liver cancer cells and found that the expression of miR-145-5p increased as detected by qPCR." (PMID 37576402, 2023). "Expressions of EZH2 and p57 proteins in small liver cancer lesions were studied." (PMID 35321452, 2022). "miR-506-3p overexpression or EZH2 knockdown could reverse the liver cancer progression induced by circSYPL1." (PMID 35345511, 2022). "Increased levels of EZH2 in cancer cells may result in tumor suppressor gene silencing, and dysregulation of EZH2 has been previously found in human liver cancer." (PMID 35253323, 2022). "Furthermore, qPCR results revealed that the expression of EZH2 in tumor tissue was obviously increased compared with adjacent tissue from patients with liver cancer." (PMID 35345511, 2022).
liver cancer (continued). "HOXB‐AS3/EZH2 complex–mediated Dicer suppression plays an important role in sorafenib resistance and cancer stemness and provides potential therapeutic strategies for diagnosing and treating liver cancer patients." (PMID 35253323, 2022). "It aimed to explore the diagnostic efficacy of multimodal ultrasound images based on mask region with convolutional neural network (M-RCNN) segmentation algorithm for small liver cancer and analyze the expression of zeste gene enhancer homolog 2 (EZH2) and p57 (P57 Kip2) genes in cancer cells." (PMID 35321452, 2022). "miR-506-3p overexpression or EZH2 knockdown could reverse liver cancer progression induced by circSYPL1." (PMID 35345511, 2022). "MiR-638 promotes cell autophagy and apoptosis through repressing EZH2 in liver cancer." (PMID 34120890, 2021). "Then the protein expression level of EZH2 in NC and miR-101 mimic groups was detected via western blotting, and it was found that miR-101 mimics remarkably suppressed the expression level of EZH2 in liver cancer cells compared with that in NC group (P<0.05)." (PMID 31966062, 2020). "Interestingly, it has been previously reported in liver cancers that EZH2 repressed, in an H3K27me3-dependent manner, the APC promoter leading to the activation of the Wnt/β-Catenin pathway." (PMID 33291363, 2020). "EZH2 is important in determining the character of hepatic tumors and immunohistochemistry results showed that this protein was positively stained in various types of malignant liver tumors." (PMID 31695969, 2019). "Furthermore, we divided liver fibrosis into four stages according to METAVIR scoring system, and detect the expression of 14-3-3σ and EZH2 in different stage of liver fibrosis (n = 110), normal tissue (n = 57) and liver cancer by qRT-PCR." (PMID 25226601, 2014). "We found high expression of EZH2 in human liver cancer cell lines." (PMID 15856046, 2005). "Thus, we hypothesized that the EZH2/H3K27me3 cascade acts as a therapeutic target of CTD-related liver cancer treatment." (PMID 37202806, 2023). "Stronger RNA binding ability and weaker DNA binding signal in tumor cells suggest that the canonical methyltransferase functions of EZH2 may be repressed in liver cancer cells, implying their novel regulatory mechanisms of EZH2 and JARID2 in promoting HCC occurrence and development." (PMID 36578923, 2022). "However, miR-506-3p overexpression or EZH2 knockdown could reverse liver cancer progression induced by circSYPL1." (PMID 35345511, 2022). "Transcription factors regulated by EZH2 may control miR-4448 expression in liver cancer cells." (PMID 24861464, 2014). "These genes, including RRM2, CCNB1, EZH2, and HMMR, are intricately involved in regulating essential cellular pathways and signaling cascades that are critical in the pathogenesis of liver cancer." (PMID 39118438, 2024). "We also showed that HOTAIR recruiting and binding PRC2 (EZH2) epigenetically represses miR-145-5p, which controls the target NUAK1, thus contributing to liver cancer cell-EMT process and accelerating tumor metastasis." (PMID 37576402, 2023). "We demonstrated a positive regulatory relationship between HOTAIR and NUAK1 in liver cancer tissues and cells and showed that HOTAIR regulates the miR-145-5p /NUAK1 axis through PRC2 (EZH2)." (PMID 37576402, 2023). "Overexpression of HOXD-AS1 competitively binds miR-130a-3p and prevents SOX4 miRNA-mediated degradation, thereby activating the expression of EZH2 and MMP2, and promoting liver cancer metastasis." (PMID 35706002, 2022). "We also found that Dicer expression was inversely correlated with HOXB‐AS3 and EZH2 expression, and negatively correlated with cancer stem cell (CSC) properties in liver cancer patients." (PMID 35253323, 2022).
liver cancer (continued). "Furthermore, we found that the EZH2 expression levels in liver cancers at advanced clinicopathological stages were significantly higher than those in tumors at early stages, implying that increased EZH2 expression may indicate tumor progression in these patients." (PMID 35627262, 2022). "Our study provided a comprehensive and distinct binding profile on RNAs and DNAs of EZH2 and JARID2 in liver cancer cell lines, suggesting their potential novel functional manners to promote HCC development." (PMID 36578923, 2022). "We observed that Dicer expression is inversely correlated with EZH2 levels, HOXB‐AS3 expression, sorafenib resistance, and cancer stem cell properties in liver cancer patients." (PMID 35253323, 2022). "In summary, we proposed a model in which EZH2 and JARID2 shift their RNA and DNA binding profiles between liver cancer and normal cell lines." (PMID 36578923, 2022). "Previous studies have shown that by forming a complex with EZH2, PVT1 promoted cell proliferation and inhibited apoptosis in liver cancer and thyroid cancer cells." (PMID 34564701, 2021). "HOXD-AS1 was bound to miR-130a-3p in a competitive manner, which activated the expression of EZH2 and MMP2 and facilitated liver cancer metastasis." (PMID 34987577, 2021). "Both the lentiviral knockdown and the pharmacological inhibition of EZH1/2 diminished the level of H3K27me3 and suppressed cell growth in liver cancer cells, compared with EZH1 or EZH2 single knockdown." (PMID 34725436, 2021). "We analyzed the expression of SMG5, EZH2, FBLL1, ZNF239, and IGF2BP3 in liver cancer using the Oncomine database." (PMID 33297932, 2020). "On HCC model studies showed that reduced one component of polycomb repressive complex 2(PRC2), enhancer of zeste homolog 2 (EZH2), effectively decreases invasion, and proliferation of liver cancer cell in vitro and in vivo." (PMID 31320544, 2019). "EZH2, a core component of PRC2 modeling complex, is highly expressed in liver cancer and liver TICs." (PMID 30545354, 2018). "Corresponding to methylome data, expression of EZH2 and other PRC2 members increased in NPC and many other types of cancers, including breast, prostate, kidney, lung, bladder, and liver cancers 41–44, and are promising therapeutic targets in cancer therapy." (PMID 25924914, 2015). "Recently, it was demonstrated that miR-101 represses HCC progression by directly targeting the enhancer of zeste homolog 2 (drosophila) (EZH2) oncogene and sensitizes liver cancer cells to chemotherapeutic treatment." (PMID 25337143, 2014). "MiR-101 targets two subunits of PRC2 complex, enhancer of zeste homolog 2 (EZH2) and EED, and was shown to play as a tumor suppressor gene in human prostate, breast and liver cancers." (PMID 20444294, 2010). "We also found that the transcriptome response to EZH2 overexpression in the liver of old mice has no similarity to the conserved gene expression signature derived from different mouse liver cancer models." (PMID 41512022, 2026). "Moreover, the clinical data analysis showed that EZH2 was positively correlated with TOP2A, which was significantly increased in liver cancer." (PMID 40271060, 2025). "Not only that, studies have shown that EZH2 can also inhibit the expression of the immune checkpoint inhibitor PD-L1 by directly upregulating the levels of CD274 and IFN regulatory factor 1 (IRF1) promoter H3K27me3 in liver cancer cells." (PMID 37626362, 2023). "In addition, HOTAIR also epigenetically downregulates miR-145-5p by binding to PRC2 (EZH2) to activate its target gene NUAK1, thereby promoting EMT in advanced stages of liver cancer." (PMID 37576402, 2023). "Specifically, promoter-rich methylated cytosine residues, non-acetylated histone 3 lysine 27 in enhancer regions, and chromatin interaction of the histone methyltransferase, EZH2, have all been identified as mechanisms of epigenetic repression for FBP1 in liver cancer." (PMID 35123542, 2022).
liver cancer (continued). "In liver cancer patient cohorts, we found that the sorafenib responder group expressed lower EZH2 levels than the sorafenib nonresponder group." (PMID 35253323, 2022). "We have understood that circSYPL1 can increase the expression of EZH2, while miR-506-3p mimics together with circSYPL1 can significantly decrease the expression of EZH2 in liver cancer cells compared with miR-506-3p negative control and circSYPL1." (PMID 35345511, 2022). "In liver cancer, EZH2 is engaged in a reciprocal negative circuit with miR-101-1, thus attenuating the tumor-suppressive role by inducing downregulation of miR-101-1." (PMID 33731131, 2021). "Lnc-b-Catm, which is highly expressed in liver cancer stem cells and recruits EZH2 (enhancer of zeste 2 polycomb repressive complex 2 subunit) to directly catalyze K49 methylation of β-catenin, inhibits the phosphorylation and subsequent ubiquitination of β-catenin." (PMID 31248165, 2019). "For the liver cancer, it found that upregulated UCA1 could promote cell growth and tumorigenesis through the signaling of HBx-UCA1/EZH2-p27Kip1 axis in hepatocarcinogenesis." (PMID 28380443, 2017). "Although, the direct H19 and EZH2 binding has not been determined in liver, EZH2 has been shown to silence tumor suppressor microRNAs in liver cancer and is upregulated in HCC." (PMID 28933364, 2017). "We also further characterized the role of HULC in liver cancer by examining the modulation of gene expression after knockdown of HULC or knockdown of two important components of chromatin-modifying complexes (MLL1 and EZH2)." (PMID 26317792, 2015). "Notably we also found that treatment of DZNep elicited remarkable suppression of EZH2, HDAC2 and CDK2 proteins with concomitant increase of miR-31 expression in liver cancer cells." (PMID 25797269, 2015). "Most of the malignant liver tumors were positive for EZH2, but neither of the adenomas, cirrhotic/dysplastic nodules, reactive and hamartomatous biliary ductules stained positively." (PMID 22809481, 2012). "CircLRIG3 is significantly up-regulated in HCC, forming a ternary complex with EZH2 and STAT3, promoting EZH2-induced STAT3 methylation and subsequent phosphorylation, leading to the activation of STAT3 signal, thereby promoting the proliferation, migration, and invasion of liver cancer cells." (PMID 35463362, 2022). "Reads density around peak center analysis also revealed the high consistency of EZH2 and H3K27me3 in THLE-2 cells, while very weak signals were detected in HepG2 cells, suggesting that the EZH2 and H3K27me3 profiles were dramatically changed in liver cancer cells." (PMID 36578923, 2022). "Overall, EZH2 c.1544A>G and CCND1 c.839A>T might be novel potential biomarkers of liver cancer." (PMID 34604069, 2021). "In conclusion, EZH2 c.1544A>G and CCND1 c.839A>T might be potential biomarkers of liver cancer." (PMID 34604069, 2021). "Our findings also suggested that EZH2 and 14-3-3σ may become hopeful biomarkers to distinguish liver cancer from non-tumor tissues." (PMID 25226601, 2014). "The inhibitory effect of miR-101 on the proliferation of liver cancer cells may be related to its inhibition on the mitogen-activated protein kinase (MAPK)/ERK signaling pathway, and the inhibition on the MAPK/ERK may be mediated by the targeted inhibition of miR-101 on EZH2." (PMID 31966062, 2020). "Combinations of EZH2 and HDAC inhibitors affected the growth of some liver cancer cells, but did not correspond to gluconeogenic gene expression." (PMID 35123542, 2022). "EZH2 is not however, specific for HCC since almost all other examined hepatic cancers: cholangiocarcinomas, hepatoblastomas and metastatic adenocarcinomas are positive as well." (PMID 22809481, 2012). "However, EZH2 is not specific for HCC, since almost all the investigated malignant liver tumors were positive as well regardless of their histogenesis." (PMID 23111165, 2012).